CETP (cholesteryl ester transfer protein)
Diseases named in the same sentence as CETP in open-access papers (continued):
Sharing a sentence is not in itself a finding about the gene and the disease.
atherosclerosis (continued). "Altogether these observations led to the concept that CETP inhibition is a powerful tool to increase HDL-C, decrease LDL-C and VLDL-C, and reduce the development of atherosclerosis." (PMID 24278703, 2012). "The epistatic effect of CETP and LIPC on HDLc concentrations and atherosclerosis has been previously reported." (PMID 22073289, 2011). "For instance, the db/db mice have been crossed with mice expressing human cholesteryl ester transfer protein (CETP); the resulting mice displayed lowered levels of VLDL and LDL and became resistant to diet-induced atherosclerosis as compared to controls." (PMID 20423497, 2010). "In contrast, raising the plasma high HDL-C level, even modestly, with the exception of inhibition of cholesteryl ester transfer protein (CETP) with torcetrapib, protects against atherosclerosis and reduces adverse cardiovascular events." (PMID 19878569, 2009). "APOE∗3-Leiden.CETP mice share the same genetic C57BL/6J background as WT mice used in previous studies with our siVwf but develop diet-induced hypercholesterolemia and subsequent atherosclerosis." (PMID 40093962, 2025). "Data on high-density lipoprotein cholesterol (HDL-c) suggested a possible causal role for atherosclerosis; nonetheless, HDL-c-raising treatments, including cholesteryl-ester transfer protein (CETP) inhibitors and niacin, failed to confirm this relationship." (PMID 38667744, 2024). "Concerning the topography of lesions, the different anatomical sites at which APOE*3-Leiden.CETP mice develop atherosclerosis have, to our knowledge, not been formally mapped." (PMID 38428154, 2024). "Since atherosclerosis is a multi-factorial disease, a new focus has been placed on developing strategies to increase the amount of high-density lipoprotein cholesterol (HDL-C), giving rise to a new era of cholesteryl ester transfer protein (CEPT) inhibitors." (PMID 38786974, 2024). "Most human and rabbit studies have suggested that CETP expression or activity promotes atherosclerosis progression, mainly through its effect of increasing non-HDL lipoproteins and decreasing HDL-cholesterol plasma levels." (PMID 37892238, 2023). "Prominent macrophage (red staining) and SAA (green staining) immunoreactivity was found in regions with extensive atherosclerosis in aortic roots of mice expressing CETP, with minimal staining in mice lacking CETP." (PMID 37004910, 2023). "In the setting of chronic inflammatory diseases with elevated SAA, the action of CETP to liberate SAA from HDL could unmask the proatherogenic activities of SAA, leading to the development of atherosclerosis." (PMID 37004910, 2023).
atherosclerosis (continued). "In APOE*3-Leiden.CETP mice (atherosclerosis model) inulin did not reduce hypercholesterolemia or atherosclerosis development and even resulted in manifestations of hepatic inflammation when combined with a high percentage of dietary cholesterol." (PMID 36678325, 2023). "SAA levels in CETP-expressing mice were generally lower compared with mice lacking CETP throughout the course of the study, indicating that CETP does not enhance atherosclerosis development by increasing plasma SAA levels." (PMID 37004910, 2023). "Rodents, which lack CETP, are naturally resistant to the development of atherosclerosis, but in studies wherein the CETP gene was introduced (i.e., knock-in transgenic models), plasma HDL-C was decreased, LDL-C increased and atherosclerosis emerged." (PMID 36012684, 2022). "The CETP link with atherosclerosis and infection has been reviewed in humans, and lower plasma CETP concentrations occurred in patients who did not survive sepsis compared to survivors." (PMID 34367144, 2021). "Atherosclerosis severity in the aortic root area of APOE*3-Leiden.CETP mice varied from type “0” (no lesions) to type “V” lesions (advanced and complex lesions)." (PMID 34052976, 2021). "This hypothesis has paved the way for developing CETP inhibitors as a possible strategy to raise HDL levels in humans, to reduce atherosclerosis and to treat CVD." (PMID 33807918, 2021). "This suggests an interaction between CETP and HDL-C in modulating atherosclerosis." (PMID 33799675, 2021). "In APOE*3Leiden.CETP mice, icosabutate reduced plasma cholesterol and TAG levels via increased hepatic uptake, upregulated hepatic lipid metabolism and downregulated inflammation pathways, and effectively decreased atherosclerosis development." (PMID 32841505, 2020). "To conclude, we demonstrate that constant light increases plasma cholesterol while decreasing circulating leukocytes in female APOE*3-Leiden.CETP mice, resulting in no net effect on atherosclerosis." (PMID 32915671, 2020). "Here, we aimed to characterize the vascular effects of PCSK9 inhibition in APOE*3Leiden.cholesteryl ester transfer protein (CETP) mice, a mouse model for familial dysbetalipoproteinemia with human-like lipoprotein metabolism, on atherosclerosis development, inflammation and EPC and CAC number." (PMID 31366894, 2019). "The present study demonstrated that the treatment with the anti-PCSK9 antibody mAb1 reduced atherosclerosis development, macrophage infiltration and cardiovascular inflammation and increased the number of EPC and CAC in APOE*3Leiden.CETP mice fed a Western type diet." (PMID 31366894, 2019). "Our data show that dietary inulin did not reduce atherosclerosis in E3L.CETP mice fed a WTD with 0.5% cholesterol." (PMID 30409998, 2018). "It has been known that mouse and rat are very resistant to develop atherosclerosis since they do not have CETP activity." (PMID 29751583, 2018). "Overall, inulin did not reduce hypercholesterolemia or atherosclerosis development in E3L.CETP mice despite showing clear prebiotic activity, but resulted in manifestations of hepatic inflammation when combined with a high percentage of dietary cholesterol." (PMID 30409998, 2018). "Additionally, mice lack cholesteryl ester transfer protein (CETP) 176, exacerbating the resistance of these animals to atherosclerosis." (PMID 26914991, 2016). "The rate of RCT in rabbits and the effects of CETP inhibitors on this rate were not studied, but the effects on development atherosclerosis were beneficial implying that RCT rate was also elevated." (PMID 26664860, 2014). "Transgenic mice expressing CETP demonstrate accelerated atherosclerosis compared with non-expressing controls." (PMID 25366166, 2014).
atherosclerosis (continued). "In rabbit models, the CETP inhibitor JTT-705 form a disulphide bond with CETP to down-regulate more than 70% of CETP activities, resulting in a 35% increase in HDL-c and inhibit the progression of atherosclerosis." (PMID 24204732, 2013). "CETP and HL are implicated in the metabolism of plasma lipoproteins, but the effects of CETP and LIPC genotypes on atherosclerosis may be dependent on LDL-receptor activity." (PMID 23181436, 2012). "However, it has been suggested that contribution of CETP to the formation of small dense LDL-C particles and impairment of NO synthesis in the presence of NOS3 G894T variants that are enhanced in hypercholesterolemia might lead to endothelial dysfunction and atherosclerosis." (PMID 23157875, 2012). "Pharmacologic CETP inhibition has increased HDL-C and reduced atherosclerosis in rabbit models." (PMID 21609439, 2011). "Since in wild type mice the plasma cholesterol (Cho) is almost completely confined to the HDL fraction while VLDL and LDL are virtually absent due to the lack of CETP, wild type mice hardly develop dyslipidemia and, as a consequence, atherosclerosis." (PMID 21611179, 2011). "However, the increase of CETP activity decreases the HDL-C level and increases the LDL-C level and atherosclerosis." (PMID 20937151, 2010). "It is reported that CETP and PLTP activities are closely related to atherosclerosis (AS)." (PMID 20937151, 2010). "However, despite the apparent lack of alterations in plasma lipoproteins in our study, CETP expression nevertheless led to significantly increased atherosclerosis in the aortic arch regions and aortic roots of apoE−/− mice." (PMID 37004910, 2023). "However, the expression of CETP did not affect atherosclerosis in apoE−/− SAA-TKO mice (6.2 ± 0.9% compared with 5.1 ± 1.1% in the presence and absence of CETP expression, respectively, P = NS), and the interaction was significant (P = 0.043)." (PMID 37004910, 2023). "The authors suggested that this increase in atherosclerosis may be due to the increased levels of VLDL and IDL cholesterol, reduced levels of HDL cholesterol, and impaired reverse cholesterol transport that was observed in the CETP transgenic mice." (PMID 37004910, 2023). "Furthermore, our data rule out the possibility that CETP enhances atherosclerosis by increasing circulating SAA concentrations." (PMID 37004910, 2023). "However, studying the lipid mediated effects of apoC1 on atherosclerosis in mice is hampered by the absence of CETP in this species, which leads to overlooking the possible impact of apoC1 on CETP-mediated remodelling of HDL as occurs in humans." (PMID 36471375, 2022). "CETP inhibition with dalcetrapib was also shown to reduce atherosclerosis, increase HDL-C, and reduce non-HDL-C in normolipidemic rabbits, but when administered to cholesterol-fed rabbits with severe hypercholesterolemia, it did not reduce atherosclerosis, despite significantly increasing HDL-C." (PMID 36012684, 2022). "Since mouse immune responses and pathways are similar to those of humans, they are a good model for studying atherosclerosis-related inflammatory responses, whereas the HDL-based lipid metabolism and the lack of CETP in mice are clear disadvantages, that are only abolished in ApoE*3-Leiden.CETP." (PMID 32714944, 2020). "Our data demonstrate a more profound effect of shifts in LD cycle on the circadian timing system of female mice, which could explain why that intervention, rather than constant light, aggravates atherosclerosis in female APOE*3-Leiden.CETP mice." (PMID 32915671, 2020). "Finally, we treated Apoe–/– mice with established atherosclerosis in analogy to the feeding study in APOE*3-Leiden.CETP mice comparing LCD with and without supplementation of 0.01% atorvastatin." (PMID 33296022, 2020).
atherosclerosis (continued). "An additional strength of our study is that we studied both male and female ApoE−/− mice, while only females could be studied in the previous study because male APOE*3 Leiden.CETP mice do not develop atherosclerosis on a cholesterol-rich diet." (PMID 32555251, 2020). "Thus, in the E3L.CETP-mice upon BAT activation, emerging cholesterol rich-remnant particles are still cleared from the circulation by the liver which subsequently protects from atherosclerosis." (PMID 30813320, 2019). "Although all of these animals are considered useful for the study of lipoprotein metabolism and atherosclerosis, it has not been defined whether their CETP is similar in terms of the molecular structures and interactions with the inhibitors." (PMID 28767652, 2017). "We aimed to address this apparent discrepancy by investigating the effects of niacin without and with simvastatin on atherosclerosis development and determine the underlying mechanisms, in APOE*3Leiden.CETP mice, a model for familial dysbetalipoproteinemia (FD)." (PMID 23840481, 2013). "Therefore, we evaluated the effects of niacin without and with simvastatin on atherosclerosis development and investigated the underlying mechanisms and contributing factors in APOE*3Leiden.CETP mice." (PMID 23840481, 2013). "The increased cholesterol accumulation in aortic arch, induced by HCD intake, was suppressed by oral administration of xanthohumol in CETP-Tg mice but not in wild-type mice, suggesting that CETP inhibition by xanthohumol prevents cholesterol accumulation leading to atherosclerosis." (PMID 23166663, 2012). "While there are some genetic differences, such as the absence of CETP and lipoprotein(a) (Lp(a)), pigs offer a favourable balance between human-like physiology, convenience in housing and handling, and the accessibility of research tools for various essential inquiries in atherosclerosis research." (PMID 39364866, 2025). "One hypothesis is that the coexistence of high CETP and high HDL-C levels might impair CE transport through the direct RCT pathway and lead to a preferential CETP-mediated CE enrichment of apoB-containing lipoproteins, resulting in enhanced atherosclerosis formation." (PMID 33799675, 2021). "Since E3L.CETP mice are a well-established model for human-like lipoprotein metabolism and atherosclerosis development, we anticipate that even in the absence of obesity, CB1R antagonism may be a promising strategy to combat CVD, probably through lowering lipids as well as inflammation." (PMID 33766515, 2021). "Although there has long been good evidence that CETP inhibition reduces atherosclerosis in rabbits, the first information on CETP as a CVD risk factor in a prospectively followed cohort was not published until after the first Phase 3 trial of a CETP inhibitor had begun." (PMID 25187879, 2014). "Therefore, E3L.CETP mice might provide a potentially useful model to study the mechanisms of the vitamin K-dependent effect on endothelial function and vascular ageing independent of atherosclerosis and vascular calcification." (PMID 40240752, 2025). "While reducing liver lipids in APOE∗3-Leiden.CETP mice, and regulating populations of circulating monocytes in LDL receptor knockout mice, SH42 did not attenuate atherosclerosis in either model." (PMID 38770137, 2024). "Cholesteryl ester transfer protein (CEPT) promotes the conversion of HDL into LDL and VLDL, as well as the exchange of TGs from VLDL to LDL and HDL, and thus, decreases the HDL-C and increases the LDL-C levels, which results in advancing ASCVD and atherosclerosis." (PMID 38338916, 2024).
atherosclerosis (continued). "Our data that the CETP-mediated increase in atherosclerosis is absent in mice lacking acute-phase SAAs provide novel insights into SAA biology and a possible mechanism for the proatherogenic effects of CETP." (PMID 37004910, 2023). "Importantly, CETP expression in apoE−/− mice did not enhance atherosclerosis by increasing circulating SAA, since SAA levels were generally lower, not higher, in mice administered AAV-CETP." (PMID 37004910, 2023). "It is not fully revealed whether CETP inhibition improves the progression of NASH and atherosclerosis, but it is worth further investigation." (PMID 25486007, 2014). "CETP action results in a CE enrichment of non-HDL lipoproteins, which could contribute to atherosclerosis." (PMID 25486007, 2014). "Similarly, xanthohumol significantly decreased the atherosclerosis index (AI, non-HDL-C/HDL-C) in CETP-Tg mice (P<0.001)." (PMID 23166663, 2012). "In contrast, PUFAs, especially ω-EPA and DHA, not only inhibit CETP and HMG-CoA reductase enzyme, lower plasma triglycerides, cholesterol, and LDL-C with little or no change in HDL-C but also are effective in arresting atherosclerosis and preventing CHD." (PMID 18922179, 2008).